TRPC1 (transient receptor potential cation channel subfamily C member 1)
Diseases named in the same sentence as TRPC1 in open-access papers (continued):
Sharing a sentence is not in itself a finding about the gene and the disease.
neurological disorders (2 papers, 2023 to 2026). "It has been commonly assumed that heteromeric TRPC1/4/5 channels are responsible for these neurological disorders." (PMID 37765099, 2023). "Given the unique expression patterns and revelations of its critical involvement in a host of neurological disorders, the TRPC1/4/5 subgroup has become an intense target of drug development, and some compounds are now in clinical trials." (PMID 37765099, 2023).
cardiac diseases (1 paper, 2022). "Our findings are critical for understanding the physiological role of TRPC1 channels and support the development of pharmacological therapies for cardiac diseases." (PMID 36620209, 2022). "An involvement of TRPC1 channels in cardiac diseases is widely established." (PMID 36620209, 2022). "Importantly, the upregulation of TRPC1 in cardiac disease was also found in human heart samples." (PMID 36620209, 2022).
movement disorder (1 paper, 2016). Neurological conditions resulting in abnormal voluntary or involuntary movement, which may impact the speed, fluency, quality and ease of movement. "The behavioral tests, i.e. swimming test, modified open field test, and sunflower seeds eating test, consistently demonstrated that TRPC1 depletion caused movement disorder in mice." (PMID 27738307, 2016). "In this study, we demonstrated that depletion of TRPC1 caused movement disorder of mice and the loss of NeuN neurons and DA neurons in basal ganglia, including the area of CPu, GPe and SNr." (PMID 27738307, 2016). "In summary, this study demonstrated that TRPC1 depletion caused movement disorder in mice and neuronal loss including DA neurons in basal ganglia." (PMID 27738307, 2016). "In this study, we reported that TRPC1 deficiency caused movement disorder as measured by swimming test, modified open field test and sunflower seeds eating test." (PMID 27738307, 2016). "Thus, it was indicated that the loss of DA neurons, resulting from cell apoptosis, consequently caused movement disorder by TRPC1 depletion." (PMID 27738307, 2016). "In our study, TRPC1 depletion was shown to cause movement disorder in the mice, which could be a consequence of the loss of the DA neurons in basal ganglia caused by TRPC1 depletion." (PMID 27738307, 2016).
myopathy (1 paper, 2020). A disease of the muscle in which the muscle fibers do not function properly. "TRPC1 binds to Homer 1, and mice lacking Homer 1 exhibit myopathy characterized by decreases in muscle fiber cross-sectional area and force generation due to constitutive Ca2+ entry thorough TRPC1 (as an SAC)." (PMID 32244622, 2020).
TRPC1 also shares sentences with these, for which no sentence is quoted: kidney diseases (3 papers); bipolar disorder (2); breast invasive carcinoma (2); cardiomyopathy (2); Glucose intolerance (2); hypertrophy (2); abdominal aortic aneurysm (1); adenocarcinoma (1); anxiety disorder (1); arteriosclerosis (1); autoimmune disease (1); Bladder (1); brain cancer (1); cervical cancer (1); cervical squamous cell carcinoma (1); channelopathies (1); Darier disease (1); dilated cardiomyopathy (1); hyperlipidemia (1); Hypocalciuria (1); Impaired glucose tolerance (1); inflammation (1); ischemic disease (1); melanoma (1); myocardial ischemia (1); ovarian adenocarcinoma (1); ovarian hyperstimulation syndrome (1); pancreatic adenocarcinoma (1); psoriasis (1); psychiatric disorder (1).
A further 4 diseases each share a sentence with TRPC1 in 1 paper.